ENSG00000259948 (VAMP (vesicle-associated membrane protein)-associated protein A, 33kDa (VAPA) pseudogene)
Synonyms: LOC124903574
Gene: Processed pseudogene on chromosome 15 (89,201,091 to 89,201,768, reverse strand). Ensembl gene ENSG00000259948.
Diseases named in the same sentence as ENSG00000259948 in open-access papers:
ENSG00000259948 is named in the same sentence as 1 disease in open-access papers, as found by Europe PMC text mining. Sharing a sentence is not in itself a finding about the gene and the disease.
ENSG00000259948 shares sentences with these, for which no sentence is quoted: infection (1 paper).